ALB (albumin)
Diseases named in the same sentence as ALB in open-access papers (continued):
Sharing a sentence is not in itself a finding about the gene and the disease.
diabetic nephropathy (continued). "It has been found that after a 6 months’ therapy with vitamin D to diabetic nephropathy patients, the urine albumin, renin and serum creatinine levels were reduced, leading to a noticeable improvement of GFR for these patients." (PMID 36984797, 2023). "Empirical clinical data have demonstrated the beneficial effects of certain Chinese herbal medicines, including symptom amelioration, reduction of urinary albumin levels, and renal function preservation in diabetic kidney disease patients." (PMID 37435493, 2023). "As a clinical consequence, diabetic kidney disease develops, which is characterized by increased urinary albumin excretion and decreased kidney function." (PMID 37370958, 2023). "In the past, the diagnosis of diabetic nephropathy generally depends on urinary albumin, serum creatinine, glomerular filtration rate and renal biopsy." (PMID 35693742, 2022). "A trial of 123 subjects with stage 3 CKD and the Effect of Topiroxostat on Urinary albumin in hyperuricemic patients with Diabetic nEphropathy (ETUDE) trial found topiroxostat reduced urinary albumin-creatinine ratio (UACR)." (PMID 36081938, 2022). "In contrast, HDL (1.2 (1.0, 1.4) mmol/L) and ALB (42.0, (39.0,44.0) g/L) were higher in non-diabetic nephropathy groups than in the diabetic nephropathy patients." (PMID 35898464, 2022). "Renal parameters for diabetic kidney disease included serum albumin, serum creatinine, albuminuria, and estimated glomerular filtration rate." (PMID 36561389, 2022). "In a randomized, placebo-controlled trial in patients with diabetic nephropathy (mean eGFR 38 mL/min/1.73 m2; median urine albumin-to-creatinine ratio 143 mg/gCr), the participants were administered a placebo or 1200 or 2400 mg/day of pirfenidone for 1 year." (PMID 36558936, 2022). "More importantly, maslinic acid treatment significantly lowered albumin and total proteins in the urine of diabetic mice, suggesting that maslinic acid protected the function of glomerulus against diabetic nephropathy." (PMID 35042497, 2022). "Due to hyperglycemia, reduced renal function and increased albumin excretion ratio arise in diabetic kidney disease (DKD)." (PMID 35878329, 2022). "The expression levels of KIM-1 and AER (albumin excretion rate) can act as a diabetic nephropathy prognostic marker." (PMID 35843953, 2022). "In this process, MAU is an early predictor of diabetic nephropathy, which reflects the balance between glomerular filtration and renal tubular reabsorption of albumin." (PMID 35295847, 2022). "Subgroup analysis also revealed that women’s risk of all-cause mortality was lower than that of men among patients with diabetic nephropathy or higher serum levels of creatinine or albumin." (PMID 35013378, 2022). "Univariate logistic regression analysis showed that gender, age, race, GGT, waist circumference, BUN, glycosylated hemoglobin, ALP, TP, UA, GLB, TG, smoking, HBP, HDL and ALB were the related factors of diabetic nephropathy." (PMID 35898464, 2022). "Patients with diabetic nephropathy have elevated IL-6, and patients with dominant proteinuria have higher serum albumin levels than patients with microalbuminuria or normal albuminuria." (PMID 35299891, 2022). "The serum KYN level was significantly elevated in patients with diabetic nephropathy and correlated positively with the urine albumin-to-creatinine ratio and negatively with GFR." (PMID 34617264, 2022). "Serum albumin, creatinine, albuminuria, and estimated glomerular filtration rate (eGFR) have been used as markers of diabetic kidney disease." (PMID 36561389, 2022). "The subgroup analysis of all-cause mortality revealed that women’s all-cause mortality risk was significantly lower than that of men among those with diabetic nephropathy or higher serum levels of creatinine or albumin." (PMID 35013378, 2022). "Patients in the early stage of diabetic nephropathy are characterized as microalbuminuria (albumin-to-creatinine ratio (ACR) of 30–299 mg/g)." (PMID 35399848, 2022).
diabetic nephropathy (continued). "Albumin transport is megalin dependent at low concentrations in diabetic nephropathy, but megalin‐independent at high concentration." (PMID 35150207, 2022). "AT1R inhibitors have been shown to ameliorate arterial blood pressure and urinary albumin excretion in T1DM patients with diabetic nephropathy as well as in hypertensive patients with T2DM." (PMID 35884947, 2022). "Diabetic nephropathy (DN), or diabetic kidney disease (DKD), is a major microvascular complication of DM and the most common cause of ESKD, characterized by the presence of increased urine albumin excretion, diabetic glomerular lesions, and loss of GFR." (PMID 35408796, 2022). "The ADA recommends annual screening for diabetic kidney disease by assessing urinary albumin excretion and GFR." (PMID 36033773, 2022). "Albuminuria further plays a role in the progression of diabetic nephropathy, and the suppression of glomerular albumin leak is a key factor in its prevention." (PMID 36139492, 2022). "We aimed to study the cut-off values of estimated glomerular filtration rate (eGFR) and the urinary albumin creatinine ratio (UACR) in the normal range for diabetic kidney disease (DKD)." (PMID 36578951, 2022). "We examined blood urea nitrogen, serum creatinine, serum glucose, total cholesterol, triglyceride, serum total protein, albumin, alanine aminotransferase, aspartate aminotransferase and 24 h urinary total protein in diabetic kidney disease rats." (PMID 36605399, 2022). "Diabetic nephropathy can be detected by the method of sequential tests of the urinary albumin levels, and the rising levels of albuminuria were related to the worse prognosis of the kidney." (PMID 35528011, 2022). "The finding of a lower rate of all-cause death in women was more robust in patients with presence of diabetic nephropathy or higher serum creatinine or albumin concentration." (PMID 35013378, 2022). "We found that there were modest but statistically correlations between albumin at 1 year and sex, age, BMI, diabetic nephropathy, urine volume, albumin, hemoglobin, as well as PD effluent protein loss at baseline." (PMID 35166186, 2022). "In patients with diabetic nephropathy, the albumin concentration in urine is higher, and the filtration of albumin-bound fatty acids is increased, further aggravating renal tubular cell damage." (PMID 35069186, 2021). "In diseases such as diabetic nephropathy, the integrity of the glomerular filtration barrier is compromised by chronic hyperglycaemia, leading to increased albumin filtration into the urine (and detectable albuminuria)." (PMID 32681438, 2021). "Diabetic kidney disease is clinically diagnosed with the presence of persistent high urine albumin-to-creatinine ratio of ≥30 mg/g and/or sustained declined in eGFR below 60 mL/min/1.73 m2." (PMID 33477404, 2021). "One study has shown that NLRP3 knockout in diabetic mice protects against diabetic nephropathy, improves the urine albumin/creatinine ratio, and attenuates glomerular hypertrophy, mesangial expansion, interstitial fibrosis, inflammation, and TGF-β1 expression." (PMID 34220546, 2021). "Diabetic nephropathy was more commonly found in those with the rs705379 TT genotype, while higher serum albumin concentrations were observed in those with the rs705379 CC genotype." (PMID 34445971, 2021). "Osteopontin is a potent molecule that induces the synthetic phenotype of mesenchymal cells and was reported to strongly correlate with urinary albumin excretion in diabetic nephropathy." (PMID 33947045, 2021). "Esaxerenone has potential renoprotective effects and reduces the urinary albumin-to-creatinine ratio (UACR) in patients with diabetic kidney disease and overt nephropathy." (PMID 34110524, 2021). "It has been reported that GLP-1 alleviates diabetic kidney disease by significantly decreasing urinary albumin and ameliorating renal pathological changes in vivo, and improves autophagy through mTOR signaling pathway." (PMID 34349660, 2021).
diabetic nephropathy (continued). "Early diabetic nephropathy is characterised by a pathological increase in glomerular permeability; then then albumin and other plasma proteins like transferrin, leak from the plasma into the urine." (PMID 34743740, 2021). "According to Sasso and colleagues, weight, albumin excretion rate, and sodium excretion reduction are of great importance in blood pressure control in diabetic patients with diabetic nephropathy." (PMID 35011042, 2021). "IL-18, produced by the inflammasome, correlates with the degree of urinary albumin excretion and is overexpressed in the tubular epithelial areas in renal tissues during diabetic nephropathy." (PMID 34830289, 2021). "The urinary albumin excretion rate (UAER) is used to clinically categorize diabetic kidney disease into the following stages: normoalbuminuria (UAER < 30 mg/g creatinine), microalbuminuria (UAER 30-300 mg/g) or macroalbuminuria (UAER > 300 mg/g)." (PMID 34909290, 2021). "The standard treatment for diabetic nephropathy includes controlling glycemia and blood pressure and reducing albumin leakage in urine using angiotensin converting enzyme inhibitors (ACEIs) or angiotensin receptor blockers (ARBs)." (PMID 34174842, 2021). "Diabetic kidney disease starts with microalbuminuria, defined as albumin excretion of 30–299 mg/day, and without treatment, it evolves into macroalbuminuria (>500 mg albumin/day) and progressive declining in the glomerular filtration rate." (PMID 34943023, 2021). "These and other reports highlight the significance of the megalin-cubilin receptor pathway in tubular cell albumin uptake and the pathogenesis of diabetic kidney disease." (PMID 32681438, 2021). "Albumin, along with other proteins, is abnormally eliminated via the urine during early stages of diabetic nephropathy." (PMID 34743740, 2021). "Diabetic nephropathy is the most common microvascular complication in diabetic patients, and abnormal urinary albumin is the primary sign of diabetic nephropathy." (PMID 32081869, 2020). "The covariates for assessing infection-related mortality included age, sex, the presence of diabetic nephropathy, dialysis history, nPCR, Kt/V for urea, body mass index, and serum concentrations of albumin, urea nitrogen, and C-reactive protein." (PMID 31988325, 2020). "Increases in osteopontin, one of the synthetic phenotype markers and an inflammatory cytokine, strongly correlate with urinary albumin excretion and glomerulosclerosis in diabetic nephropathy." (PMID 32093382, 2020). "MicroRNA-451 expression in blood and plasma using real-time PCR was evaluated in addition to the classic diabetic nephropathy markers (serum creatinine, urinary albumin, and eGFR)." (PMID 32855824, 2020). "Diabetic kidney disease (DKD) is diagnosed by the persistent presence of elevated urinary albumin excretion and/or low glomerular filtration rate." (PMID 32726619, 2020). "Impaired glomerular filtration membrane barrier function in patients with diabetic nephropathy often leads to increased excretion of albumin in urine, increased serum creatinine, and blood urea nitrogen." (PMID 32143429, 2020). "Surprisingly, there were 9 significant differentially-expressed proteins, including albumin which is currently used as a biomarker for diabetic nephropathy." (PMID 32665774, 2020). "Four experimental kidney disease models include cisplatin-induced and lipopolysaccharide (LPS)-induced AKI, streptozocin-induced diabetic nephropathy (DN), and cationized-bovine serum albumin (c-BSA)-induced membranous nephropathy (MN), respectively." (PMID 32630021, 2020). "In phase II and III studies, esaxerenone plus a renin–angiotensin system inhibitor markedly reduced the urinary albumin-to-creatinine ratio (UACR) in hypertensive patients with diabetic nephropathy." (PMID 32616846, 2020).
diabetic nephropathy (continued). "Treatment of STZ-induced, diabetic, Sprague–Dawley rats with curcumin (50 mg/kg b.w./day) for 6 weeks attenuated diabetic nephropathy with significantly reduced blood urea nitrogen, and creatinine while albumin was increased." (PMID 31881654, 2019). "Further, it was observed that SPP can significantly decrease the 24 hour urine volume and urinary albumin in mice, recover renal damage and prevent the occurrence and development of diabetic nephropathy." (PMID 35518685, 2019). "The expression of specific transporters like the cubilin and megalin (LRP2) receptors, which mediate the endocytosis of albumin, suggests that this cell line is highly suitable for studying the implications of diabetic kidney disease and albuminuria." (PMID 31554337, 2019). "The six-week low-energy extracorporeal shock wave therapy regimen decreased urinary albumin excretion as well as reduced glomerular hypertrophy and renal fibrosis in the rat model of diabetic nephropathy." (PMID 31354913, 2019). "Albuminuria is preceded by biomarkers of both glomerular and tubular dysfunction, suggesting albumin as a late indicator of diabetic kidney disease." (PMID 30591810, 2019). "This study shows the importance of including highly concentrated albumin in in vitro studies for mimicking diabetic kidney disease." (PMID 31554337, 2019). "Urine albumin is currently used in diagnosis and prognosis diabetic nephropathy while urinary nephrin and L-FABP are indicators of glomerular and tubulointerstial injury that occurs in the early stages of kidney disease." (PMID 30591810, 2019). "This choice was based on its ease of measurement using POC technology and the fact that the urine albumin:creatinine ratio is a commonly used indicator of diabetic nephropathy." (PMID 29953520, 2018). "In this study, we retrospectively evaluated the effects of RAS inhibitor therapy on diabetic nephropathy in Japanese subjects whose urinary albumin levels were within normal range." (PMID 30525055, 2018). "Our data contrast with a study showing increase p66Shc expression in PBMCs of patients with diabetic nephropathy and correlation with albumin excretion and disease duration." (PMID 29343271, 2018). "Previous studies have traditionally used urinary albumin excretion as an indicator of the presence of diabetic kidney disease, along with estimates of glomerular filtration rate." (PMID 29910771, 2018). "There were significant differences in sex, presence of diabetic nephropathy, HD vintage, serum albumin, serum phosphate, C-reactive protein, intact parathyroid hormone, Kt/V, and GNRI." (PMID 29558928, 2018). "Urinary type IV collagen (U-Col4) and albumin excretion is evaluated to monitor the development of diabetic kidney disease." (PMID 29624611, 2018). "In clinical practice, diabetic nephropathy is diagnosed either when GFR falls to less than 60 ml/min or the urine albumin excretion exceeds 30 mg/gram creatinine." (PMID 30729117, 2018). "Elevated urinary albumin excretion (microalbuminuria) is an early marker of diabetic nephropathy, but there is an unmet need for better biomarkers that capture the individuals at risk with higher accuracy and earlier than the current markers do." (PMID 30217994, 2018). "Microalbumin is an outcome predictor in patients with renal disease, as such; the determination of minimum levels of urinary albumin excretion (microalbuminuria) can be implied for incipient diabetic kidney disease." (PMID 29805343, 2018). "Despite this, many studies continue to use urinary albumin excretion alone to determine the presence of diabetic kidney disease." (PMID 29910771, 2018). "It is important to recognize the limitations of using urinary albumin excretion alone in patients with type 2 diabetes to determine presence of diabetic kidney disease." (PMID 29910771, 2018).
diabetic nephropathy (continued). "Because our Ps’alb assay measures albumin permeability directly, it circumvents this potential confounding factor and confirms that glomeruli are a target in diabetic kidney disease." (PMID 29433915, 2018). "Only subjects with diabetic nephropathy or urine microalbuminuria-positive defined as Urine Albumin to Creatinine Ratio (UACR) >10 mg/mmol were recruited into a prospective, randomized, double-blinded, placebo-controlled trial." (PMID 30227659, 2018). "Urine albumin excretion was 15.68±3.461 mg/24 hours in the control group (Control) and increased to 49.19±11.01 mg/24 hours (P< 0.01) in mice with diabetic nephropathy (DN+DMSO)." (PMID 29425253, 2018). "RTN1A-mediated ER stress and apoptosis contribute to tubular cell injury in diabetic nephropathy, albumin overload-induced nephropathy and AKI murine models." (PMID 29340054, 2017). "Urinary albumin excretion ranging between 30 and 300 mg/24 h (microalbuminuria) is the earliest sign of diabetic kidney disease (DKD)." (PMID 28596971, 2017). "Differing from albumin in terms of their molecular radii and isoelectric points, urinary ceruloplasmin and TF have been shown to predict the onset of microalbuminuria in diabetic nephropathy." (PMID 27590021, 2017). "Here, we show that transfection with the VEGF-A inhibitor gene sFlt-1 in mice with diabetic nephropathy reverses pre-existing kidney damage by normalising albumin:creatinine levels and mesangial matrix content." (PMID 28620823, 2017). "Among mediators of fibrosis, albumin was the most potent stimulus of miR-184, consistent with the putative role of albuminuria in exacerbating disease progression in diabetic nephropathy." (PMID 28364255, 2017). "Diabetic nephropathy is a syndrome characterized by a progressive increase in the excretion of urinary albumin, elevated blood pressure coupled with glomerular lesions leading ultimately to loss of glomerular filtration and eventually end stage renal failure." (PMID 28201997, 2017). "The addition of aliskiren and losartan reduced urinary albumin excretion in patients with diabetic nephropathy." (PMID 29184499, 2017). "Patients with diabetic nephropathy suffer from impaired albumin reabsorption by proximal tubular epithelial cells." (PMID 29203863, 2017). "The primary outcome was time to onset of diabetic nephropathy, defined by persistent albuminuria in overnight specimens, with a urinary albumin excretion rate >200 mcg/min and at least 30% higher than the baseline level." (PMID 28725272, 2017). "Renal clearance function and urinary albumin excretion are important markers for diabetic nephropathy." (PMID 26871846, 2016). "TXNIP is significantly increased in rats and humans with diabetic nephropathy and closely correlated with urinary albumin, renal fibrosis, and reactive oxygen species." (PMID 26881256, 2016). "On the other side, BA has a preventing effect on diabetic nephropathy by amelioration of plasma albumin, BUN, Cr and renal histology changes during diabetic situation." (PMID 27921024, 2016). "Increases in creatinine clearance and urinary albumin excretion resemble early signs of diabetic nephropathy." (PMID 27253523, 2016). "The differences among four groups were observed in estimated GFR, sex, CKD stages, diabetic nephropathy, hemoglobin, albumin, uric acid, potassium, Na-Cl and proteinuria." (PMID 27123981, 2016). "Diabetic kidney disease – which is defined by elevated urine albumin excretion or reduced glomerular filtration rate (GFR) or both – is a serious complication that occurs in 20% to 40% of all diabetics." (PMID 28197499, 2016). "The first clinical sign of diabetic nephropathy is the microalbuminuria, which is based on the measurement of urinary albumin excretion." (PMID 27253523, 2016). "Increases in serum cTnT were associated with higher cTnT concentrations in the present cross-sectional study (age, eQB, serum phosphorus, serum CRP, diabetic nephropathy, and serum albumin), consistent with previous studies." (PMID 26603871, 2016).